RNU6-148P (RNA, U6 small nuclear 148, pseudogene)
Gene: Small nuclear RNA gene on chromosome 12 (89,754,059 to 89,754,152, forward strand). Ensembl gene ENSG00000252823.
Homologues: Orthologues: chimpanzee U6 (100% identical), macaque U6 (99% identical), dog U6 (86% identical), pig U6 (86% identical), guinea pig U6 (82% identical). Paralogues in human: RNU6-43P (91% identical), RNU6-19P (88% identical), RNU6-24P (88% identical), RNU6-398P (88% identical), RNU6-1060P (87% identical), RNU6-11P (87% identical), RNU6-1216P (87% identical), RNU6-199P (87% identical), RNU6-28P (87% identical), RNU6-34P (87% identical), RNU6-37P (87% identical), RNU6-698P (87% identical), and 1287 more.